PINLYP (phospholipase A2 inhibitor and LY6/PLAUR domain containing)
Tractability: Antibody: UniProt places it where antibodies can reach, with high confidence; UniProt predicts a signal peptide or a membrane-spanning region; its Gene Ontology location is reachable by antibodies, with medium confidence.
Gene: Protein-coding gene on chromosome 19 (43,575,801 to 43,583,964, forward strand). Ensembl gene ENSG00000234465.
Subcellular location: Secreted
Subcellular location (Human Protein Atlas): Microtubules; Primary cilium; Vesicles; Basal body; Centrosome; Cytokinetic bridge; Mitotic spindle; Predicted to be secreted
Gene Ontology:
Molecular function: phospholipase inhibitor activity
Cellular component: extracellular region
Genetic constraint (gnomAD): Loss-of-function variants: 10 observed, 13.27 expected, observed/expected ratio (o/e) 0.75, 90% interval 0.46 to 1.28. The upper end of that interval is the gene's LOEUF score, 1.28, which puts it in group 5 of 6, group 1 being the genes least tolerant of losing a copy. Missense variants: 259 observed, 248.97 expected, observed/expected ratio (o/e) 1.04, 90% interval 0.94 to 1.15. Synonymous variants: 85 observed, 91.3 expected, observed/expected ratio (o/e) 0.93, 90% interval 0.78 to 1.12.
Homologues: Orthologues: chimpanzee PINLYP (99% identical), macaque PINLYP (88% identical), dog PINLYP (55% identical), mouse Pinlyp (55% identical), rat Pinlyp (54% identical), zebrafish ly6m3 (24% identical), zebrafish ly6m6 (23% identical), zebrafish ly6m7 (23% identical), zebrafish si:ch211-134a4.6 (23% identical), zebrafish ly6m4 (22% identical), tropical clawed frog XB5760648 (22% identical), zebrafish ly6m2 (21% identical), and 3 more. Paralogues in human: LYPD8 (18% identical).
Diseases named in the same sentence as PINLYP in open-access papers:
PINLYP is named in the same sentence as 7 diseases in open-access papers, as found by Europe PMC text mining. Sharing a sentence is not in itself a finding about the gene and the disease. The quoted sentences say what the papers report.
herpesvirus infection (1 paper, 2025). "Our results reveal that KSHV hijacks the host factor PINLYP to change phospholipid metabolism for benefiting its latent infection, providing a new target for controlling herpesvirus infection." (PMID 40373067, 2025).
latent infection (1 paper, 2025). "Interesting, we observed that de novo KSHV infection of HUVECs induces PINLYP expression until the establishment of KSHV latent infection in the infected cells, indicating that PINLYP expression might be beneficial for KSHV latent infection." (PMID 40373067, 2025). "Here, we uncovered the crucial role of PINLYP in phospholipid metabolism reprogramming, especially in TAG biosynthesis during KSHV latent infection." (PMID 40373067, 2025). "Furthermore, the genome copies of KSHV and expression of viral latent and lytic genes were also markedly increased in PINLYP KO cells prior to Dox treatment, highlighting the important role of PINLYP in inhibiting KSHV lytic reactivation to facilitate viral latent infection." (PMID 40373067, 2025).
lymphoma (1 paper, 2025). A malignant (clonal) proliferation of B- lymphocytes or T- lymphocytes which involves the lymph nodes, bone marrow and/or extranodal sites. "We previously characterized a new gene PINLYP that was identified in a murine gammaherpesvirus 68 (MHV68)-associated lymphoma model and showed that PINLYP positively regulates type I IFN innate immunity and protects the host against virus infection." (PMID 40373067, 2025).
virus infection (1 paper, 2025). "PINLYP belongs to the Ly6/uPAR superfamily, whose expression can be induced or suppressed by viral infection." (PMID 40373067, 2025). "Our previous work reported that PINLYP interacts with TBK1, induces type I interferon (IFN) production, and protects the host against viral infection." (PMID 40373067, 2025). "We have previously reported that PINLYP regulates type I IFN innate immunity and protects the host against virus infection." (PMID 40373067, 2025).
infection (1 paper, 2025). The state of being infected such as from the introduction of a foreign agent such as serum, vaccine, antigenic substance or organism. "Given that KSHV de novo infection of HUVECs induces PINLYP expression, our data highlight that KSHV hijacks the cellular factor PINLYP to remodel phospholipid metabolism, particularly TAG biosynthesis, in favor of its own latency." (PMID 40373067, 2025). "This indicates that KSHV induces PINLYP expression during the temporary lytic phase of de novo infection and that PINLYP induction reaches a steady state when KSHV starts the entry into the latent phase." (PMID 40373067, 2025). "Notably, KSHV de novo infection of HUVEC resulted in a gradual increase of PINLYP expression by 72 h post-infection, accompanied by a gradual decrease of KSHV RTA, ORF46, and K8.1 lytic gene expression." (PMID 40373067, 2025).
PINLYP also shares sentences with these, for which no sentence is quoted: immune disorders (1 paper); preeclampsia (1).